Y_RNA (Y RNA )
Gene: Miscellaneous RNA gene on chromosome 17 (38,231,043 to 38,231,144, reverse strand). Ensembl gene ENSG00000274284.
Homologues: Orthologues: chimpanzee Y_RNA (96% identical), macaque Y_RNA (93% identical). Paralogues in human: Y_RNA (100% identical), Y_RNA (98% identical), Y_RNA (87% identical), RNY3 (86% identical), Y_RNA (86% identical), Y_RNA (85% identical), RNY3P1 (84% identical), Y_RNA (84% identical), Y_RNA (83% identical), RNY3P9 (82% identical), Y_RNA (82% identical), RNY3P16 (81% identical), and 95 more.